RNU6-1168P (RNA, U6 small nuclear 1168, pseudogene)
Gene: Small nuclear RNA gene on chromosome 2 (88,383,494 to 88,383,597, reverse strand). Ensembl gene ENSG00000212133.
Homologues: Orthologues: chimpanzee U6 (99% identical), macaque U6 (90% identical), pig U6 (85% identical), rabbit U6 (77% identical), dog U6 (70% identical), rat LOC120095355 (69% identical). Paralogues in human: RNU6-1331P (85% identical), RNU6-1094P (84% identical), RNU6-28P (84% identical), RNU6-29P (84% identical), RNU6-38P (84% identical), RNU6-727P (84% identical), RNU6-797P (84% identical), RNU6-1056P (83% identical), RNU6-1124P (83% identical), RNU6-25P (83% identical), RNU6-43P (83% identical), RNU6-1 (82% identical), and 1286 more.